SOCS1 (suppressor of cytokine signaling 1)
Description:
Essential negative regulator of type I and type II interferon (IFN) signaling, as well as that of other cytokines, including IL2, IL4, IL6 and leukemia inhibitory factor (LIF). Downregulates cytokine signaling by inhibiting the JAK/STAT signaling pathway. Acts by binding to JAK proteins and to IFNGR1 and inhibiting their kinase activity. In vitro, suppresses Tec protein-tyrosine activity. Regulates IFN-gamma (IFNG)- mediated sensory neuron survival (By similarity). Probable substrate recognition component of an ECS (Elongin BC-CUL2/5-SOCS-box protein) E3 ubiquitin ligase complex which mediates the ubiquitination and subsequent proteasomal degradation of target proteins.
Synonyms: SOCS-1; JAB; SSI-1; TIP-3; SSI1; TIP3; Cish1; AISIMD; CIS1
Tractability: No criterion of Open Targets' tractability assessment is met for any kind of drug.
Gene: Protein-coding gene on chromosome 16 (11,249,101 to 11,256,556, reverse strand). Ensembl gene ENSG00000185338.
Subcellular location: Nucleus; Cytoplasmic vesicle
Subcellular location (Human Protein Atlas): Nucleoplasm; Vesicles
Pathways (Reactome):
Immune System: Antigen processing: Ubiquitination & Proteasome degradation; Growth hormone receptor signaling; Inactivation of CSF3 (G-CSF) signaling; Interferon alpha/beta signaling; Interferon gamma signaling; Interleukin-4 and Interleukin-13 signaling; Interleukin-7 signaling; MyD88:MAL(TIRAP) cascade initiated on plasma membrane; Regulation of IFNA/IFNB signaling; Regulation of IFNG signaling; Signaling by CSF3 (G-CSF)
Signal Transduction: Regulation of KIT signaling
Gene Ontology:
Molecular function: insulin-like growth factor receptor binding; protein binding; protein kinase binding; cytokine receptor binding; kinase inhibitor activity; protein kinase inhibitor activity
Biological process: macrophage differentiation; negative regulation of receptor signaling pathway via JAK-STAT; positive regulation of regulatory T cell differentiation; cytokine-mediated signaling pathway; negative regulation of CD8-positive, alpha-beta T cell differentiation; negative regulation of insulin receptor signaling pathway; positive regulation of CD4-positive, alpha-beta T cell differentiation; developmental process; intracellular signal transduction; protein ubiquitination
Cellular component: nucleoplasm; cytoplasm; cytosol; cytoplasmic vesicle; nucleus
Genetic constraint (gnomAD): Loss-of-function variants: 3 observed, 5.11 expected, observed/expected ratio (o/e) 0.59, 90% interval 0.27 to 1.47. That is too few expected variants to judge how well the gene tolerates losing a copy. Missense variants: 368 observed, 248.54 expected, observed/expected ratio (o/e) 1.48, 90% interval 1.36 to 1.61. Synonymous variants: 194 observed, 110.71 expected, observed/expected ratio (o/e) 1.75, 90% interval 1.56 to 1.94.
Gene-disease validity (ClinGen):
ClinGen rates the evidence that SOCS1 causes each of these diseases.
autoinflammatory syndrome with immunodeficiency (autosomal dominant): Definitive. An autoinflammatory syndrome characterized by onset of various autoimmune features usually in the first decades of life, although later onset has been reported.
Cancer hallmarks: escaping immune response to cancer (promotes); proliferative signalling (promotes); genome instability and mutations (suppresses); escaping programmed cell death (promotes); invasion and metastasis (promotes); invasion and metastasis (suppresses); change of cellular energetics; tumour promoting inflammation (suppresses); angiogenesis; suppression of growth (promotes); escaping programmed cell death (suppresses)
Homologues: Orthologues: chimpanzee SOCS1 (99% identical), macaque SOCS1 (99% identical), pig SOCS1 (98% identical), guinea pig SOCS1 (96% identical), mouse Socs1 (96% identical), rat Socs1 (96% identical), tropical clawed frog socs1 (59% identical), zebrafish socs1a (40% identical), Drosophila melanogaster Socs44A (23% identical), Drosophila melanogaster Socs36E (20% identical). Paralogues in human: CISH (28% identical), SOCS3 (28% identical), SOCS2 (26% identical), SOCS6 (25% identical), SOCS5 (23% identical), SOCS7 (23% identical), SOCS4 (20% identical).
Diseases named in the same sentence as SOCS1 in open-access papers:
SOCS1 is named in the same sentence as 356 diseases in open-access papers, as found by Europe PMC text mining. Sharing a sentence is not in itself a finding about the gene and the disease. The quoted sentences say what the papers report.
breast carcinoma (74 papers, 2003 to 2025). "Higher expressions of SOCS1, 3, 4, and 7 are associated with good prognosis in breast cancer, and STAT3 is constitutively activated in breast cancer." (PMID 37064130, 2023). "Higher expression levels of SOCS1 are associated with earlier tumor stages and better clinical outcomes in human breast cancer patients." (PMID 35859293, 2022). "A recent study suggested that SOCS1 expression was low in breast cancer tissues and its expression level was associated with different clinical stages of breast cancer." (PMID 34120621, 2021). "Differing from Socs1, Cyclin D1 is overexpressed in more than 50% of breast cancer, encoding the regulatory subunit of a holoenzyme that phosphorylates the gene retinoblastoma (RB) and promotes G1/S cell cycle progression and oncogenesis." (PMID 32631271, 2020). "Loss of SOCS1 has been observed in human cancers, including hepatocellular carcinoma, breast cancer, acute myeloid leukemia, and ESCC." (PMID 31728180, 2019). "Breast cancer patients with positive expression of SOCS1 protein exhibit a decreased risk of detectable circulating tumor cells in the peripheral blood." (PMID 28228755, 2017). "High expression level of SOCS1 mRNA is associated with early tumor stages and improved clinical outcomes in breast cancer." (PMID 28228755, 2017). "Higher mRNA expression levels of SOCS1, 3, 4 and 7 are significantly associated with earlier tumour stage and better clinical outcome in human breast cancer." (PMID 20433750, 2010). "Downregulated SOCS1 expression in various human cancers has been associated with dysregulation of cytokine receptor signaling pathways, whereas upregulated SOCS1 expression is associated with earlier tumor stages and better clinical outcomes in breast cancer." (PMID 30450337, 2018). "It is also involved in suppression of cytokine signaling 1 (SOCS1) implicated in cancer metastasis, cell cycle, adherence junctions, and interactions between the extracellular matrix and receptors leading to brain metastases in patients with advanced breast cancer." (PMID 39218619, 2024). "At the protein level, FTH1, ISCU, and SOCS1 were medium stained in breast cancer tissues on the Human Protein Atlas (HPA) portal." (PMID 40463869, 2025). "In the present investigation, we noted a rise in SOCS1 expression in breast cancer, a finding consistent with Mahller’s research on MPNST cells." (PMID 39850819, 2024). "In other malignancies, including breast cancer and multiple myeloma, elevated expression of microRNAs targeting the SOCS1 gene, emerges as a mechanism contributing to cancer development." (PMID 38711523, 2024). "This is the first report that shows that the chemically engineered gold nanoparticles conjugated with citrate inhibit IFN-γ induced SOCS1 mRNA/protein expression via modulating miRNA-155-5p in triple-negative human breast cancer cells." (PMID 37720228, 2023). "For instance, SOCS1 downregulation was described in hepatocellular carcinoma, cervical, ovarian and breast cancer." (PMID 35413796, 2022). "Aberrant activation of the JAK/STAT3 pathway due to down-regulation of SOCS1 by miR-155 is observed in solid tumors, such as breast cancer and laryngeal carcinoma." (PMID 36505769, 2022). "Higher expression levels of SOCS1, SOCS3, SOCS4, and SOCS7 have all been reported to associate with better prognosis in human breast cancer." (PMID 33758600, 2021). "The overexpression of NDRG2 in MBA-MB231 breast cancer cells increases SOCS-1 expression, and the JAK/STAT3 pathway is negatively regulated by SOCS-1." (PMID 34685629, 2021). "In breast cancer miR-155 functions as an oncomir by targeting the suppressor of cytokine signaling one gene (SOCS1)." (PMID 34179081, 2021). "In total, the results strongly suggested CXCL9, CCR7, and SOCS1 played an important role in chemo-resistance of breast cancer." (PMID 32974144, 2020).
breast carcinoma (continued). "All the outcomes strongly confirmed that CXCL9, CCR7, and SOCS1 screened out via WGCNA participated in the regulation of taxanes-sensitivity in breast cancer cells." (PMID 32974144, 2020). "In conclusion, our study shed light on clinical theragnostic relationships between miR-335-5p/CXCL9, let-7c-5p/CCR7/SOCS1 axes, and taxanes-resistance in breast cancer." (PMID 32974144, 2020). "More importantly, the mRNA expressions of CXCL9, CCR7, and SOCS1 in breast cancer cells were observed notably higher in the taxanes-sensitive cell lines (MCF-7 and BCap37) than taxanes-resistant cell lines (MCF-7/T and Bads-200)." (PMID 32974144, 2020). "Another example is miR-155, which acts as an oncogene in breast cancer by inhibiting SOCS1 and consequently increasing proliferation and inflammation." (PMID 32338277, 2020). "For instance, while SOCS1 was downregulated in about two third of breast cancer tissues compared with the corresponding ANCTs, it was upregulated in the remaining samples." (PMID 30453988, 2018). "SOCS1 hypermethylation is detected in myeloid leukemia, lymphoma, Barrett’s adenocarcinoma, and breast cancer." (PMID 28228755, 2017). "SOCS3 and SOCS1 expression has been widely investigated in a number of cancers, including breast cancer, multiple myeloma, hepatocarcinoma and lymphoma, where their absence suggests a tumor-suppressor function." (PMID 28445952, 2017). "A previous study indicated that SOCS1 is an evolutionarily conserved target of miR-155 in breast cancer cells." (PMID 27811366, 2016). "In human breast cancer, the mRNA expression of SOCS1 decreases as TNM stage increases, and high SOCS1 expression is significantly associated with earlier tumor stage and a better clinical outcome." (PMID 25893382, 2015). "The other study compared the expression differences of SOCS1-7 between breast cancer tissue and background breast tissue." (PMID 26437444, 2015). "In 2010, Jiang and coworkers demonstrated that miR-155 targeted the tumor suppressor gene Socs1 (suppressor of cytokine signaling 1 gene) in human breast cancer cells, promoting cell proliferation, colony formation, and xenograft tumor growth." (PMID 23965974, 2013). "Recently, a new study found that miR-155 targeting suppressor of cytokine signaling 1 (SOCS1) who inhibit STAT3 functions as an oncomicroRNA in a breast cancer cell line." (PMID 23437123, 2013). "Many investigations indicated that SOCS1 played an important role in many malignancies, including colon cancer, liver cancer, lung cancer, pancreatic cancer and breast cancer." (PMID 23437123, 2013). "Recently, a new investigation reported that miR-155 functions as an oncomicroRNA in breast cancer,which decrease the expression of suppressor of cytokine signaling 1 (SOCS1) in breast cancer cell lines." (PMID 23437123, 2013). "The tumor-suppressor gene suppressor of cytokine signaling 1 (SOCS1) has been identified as a target of miR-155 in breast cancer cell lines." (PMID 23202960, 2012). "The expression of SOCS1 was found to be inversely correlated to miR-155 expression in human breast cancer cells." (PMID 23202960, 2012). "Earlier studies indicated that miR-155 and SOCS1 interacted in regulatory T cells, macrophages and human breast cancer cells." (PMID 21762537, 2011). "MiR-155 promoted the proliferation of breast cancer cells through down-regulation of SOCS1 (Suppressor of cytokine signaling 1) and FOXO3a (Forkhead box O3)." (PMID 21541331, 2011). "Patients who remained disease-free had higher levels of SOCS1 and 2 expression compared to those who died from breast cancer." (PMID 20433750, 2010). "In this study, we examined the expression of SOCS1-7 genes in normal and breast cancer tissue and correlated this with several clinico-pathological and prognostic factors." (PMID 20433750, 2010). "Patients who remained disease-free had higher levels of SOCS1 and 2 expression compared to those who died from breast cancer (p = 0.02 and p = 0.033 respectively)." (PMID 20433750, 2010).
breast carcinoma (continued). "The present study is aimed to elucidate the clinicopathological features associated with SOCS1, SOCS2, SOCS3, CIS and IGF-I expression in breast cancer." (PMID 17651480, 2007). "In sections obtained from patients with infiltrating breast carcinoma, SOCS-1–3, and CIS transcript expression was stronger in the region corresponding to the most active zone of the tumour." (PMID 12888825, 2003). "SOCS-1 has been shown to be critical for preventing interferon γ (IFNγ)-mediated growth arrest of M-1 myeloid cells, and overexpression of SOCS-1 or SOCS-3 in breast cancer lines inhibits the antiviral and antiproliferative ability of IFNγ." (PMID 12888825, 2003). "A survey of 10 breast cancer lines for SOCS-1–3 and CIS transcripts showed that only CIS mRNA was elevated in all transformed lines in comparison with the two phenotypically normal lines, HMEC184 and MCF-10A." (PMID 12888825, 2003). "In view of the importance of SOCS expression in regulation of mammary cell function, and its potential importance in breast cancer, we have examined the expression of SOCS-1–3 and CIS in both breast cancers and in breast cancer lines." (PMID 12888825, 2003). "Therefore, there is a preliminary belief that miR-155 plays a vital role in the proliferation and migration of breast cancer cells by reducing the expression of SOCS1 through its targeting of the 3`UTR of SOCS1 mRNA sequence." (PMID 37720228, 2023). "The study reports that high expression levels of miR-155 in breast cancer cells downregulated suppressor of cytokine signaling 1 (SOCS1), increased the phosphorylated STAT1 (pSTAT1)/pSTAT3 ratio, and thereby stimulated chemoattractants for tumor infiltration of effector T cells." (PMID 36189796, 2022). "Taken together, these results suggest that miR-155 in breast cancer cells enhances CXCL9/10/11 expression by suppressing SOCS1 expression and tilting the p-STAT1/p-STAT3 ratio, leading to the recruitment of effective T cells to the tumor site and subsequently an improved antitumor immune response." (PMID 35925680, 2022). "Indeed, tumor cell invasiveness and metastasis is regulated by the effect of miR155 on the STAT3-SOCS1 pathway and SOCS1 function is reduced in human breast cancer cells expressing high levels of miR155." (PMID 33946612, 2021). "Indeed, the suppressor of cytokine signaling 1 (SOCS1) is a critical regulator of immune cell function and an evolutionarily conserved target of miR-155 in breast cancer cells." (PMID 34359591, 2021). "Similarly, it has been shown that 5-AZA-CdR can re-activate SOCS1 expression in breast cancer cells." (PMID 32337014, 2020). "Socs1 is downregulated in breast cancer, functioning as a tumor suppressor." (PMID 32631271, 2020). "Suppressor of cytokine signaling 1 (SOCS1) recently served as a novel miR-155 target in breast cancer, and might also exerted roles in OSCC." (PMID 31133028, 2019). "Moreover, hypermethylation of SOCS1 promoter has been shown in hepatocellular carcinoma, cervical cancer, and ovarian and breast cancer cells." (PMID 30453988, 2018). "In some cases, miR-155 expression is inversely correlated with SOCS1, as shown in breast cancer." (PMID 29066622, 2017). "Ectopic expression of NDRG2 inhibits the tumor growth through inducing suppressor of cytokine signaling 1 and subsequent inactivation of signal transducer and activator of transcription 3 in breast cancer cells or by attenuating the AP-1 activity in colon carcinoma cells." (PMID 25889839, 2015). "Moreover, NDRG2 expression negatively regulates JAK2/STAT3 through the regulation of the suppressor of cytokine signaling 1 gene in breast cancer cells." (PMID 25061501, 2014). "miR-155 has been shown to target SOCS1 in macrophages, positively regulating the host anti-viral response by promoting type I IFN signalling; and in breast cancer cells, miR-155 suppression of SOCS1 plays an oncogenic role resulting in the constitutive activation of the JAK-STAT pathway." (PMID 23894411, 2013).